IL6 (interleukin 6)
Diseases named in the same sentence as IL6 in open-access papers (continued):
Sharing a sentence is not in itself a finding about the gene and the disease.
cervical carcinoma (continued). "On the basis of high microenvironmental IL-6 levels promoting cervical cancer development and angiogenesis, inhibition of the biological activity of IL-6 may be potentially beneficial for the treatment of cervical cancer." (PMID 31470515, 2019). "The study suggests IL6 may play a role in the process of endometrium carcinogenesis (leading to endometrial cancer)." (PMID 30828987, 2019). "Also, results indicate that KP can impede the anti-apoptotic role of interleukin-6, which is normally required for maintaining cervical cancer cell survival." (PMID 31470515, 2019). "On the basis of these previous reports, NF-kB may be involved in EGF-induced IL-6 production in HeLa cervical cancer cells." (PMID 31470515, 2019). "However, activated lymphocytes, bone marrow cells, mononuclear macrophages, and some cancer cells (including cervical cancer cells) can produce IL-6, which is an important factor promoting the progression of the disease and the development of tumors." (PMID 31297140, 2019). "Additionally, estrogen has been demonstrated as a key negative regulator of IL6 production in cervical cancer HeLa cells." (PMID 30510575, 2018). "Such phenomenon might be due to that rs1800795 of the IL-6 gene promoter influences the binding of the glucocorticoid receptor and thus represses transcriptional activation, which lead to the development of cervical cancer." (PMID 30135142, 2018). "Thus it also should be cautious about the role of IL-6 -174G>C in cervical cancer, because age, smoking and drinking status, exposing factors, and gene–environment interactions were not fully adjusted in original studies." (PMID 30135142, 2018). "Notably, it has been shown that M2 macrophage differentiation is driven by cervical cancer-derived IL-6 together with prostaglandin E2." (PMID 28895886, 2017). "Clinically most relevant, IL-6 expression is associated with a negative prognosis for cervical cancer patients further highlighting its pivotal role in linking chronic inflammation and progression to invasive cancer." (PMID 28895886, 2017). "This suggests that the IL-6/JAK/STAT3 signaling pathway might be an interesting target to revert immune deviation in cervical cancer." (PMID 28895886, 2017). "Thus, cervical cancer-derived IL-6 immobilizes dendritic cells in the tumor stroma via CCR7 suppression facilitating local MMP-9 production." (PMID 28895886, 2017). "In terms of mechanism, LYN could also promote cervical cancer cells metastasis through activating IL-6/STAT3 pathway." (PMID 27690342, 2016). "Cervical cancer SiHa and C33a cells were treated with IL-6 (5, 10, 25, 50 ng/ml) for 48 hours." (PMID 27690342, 2016). "Similarly, the supernatant of PDT-treated human cervical carcinoma (HeLa) cells induced increased IL-6 secretion from macrophages." (PMID 26307977, 2015). "Previously, we reported that IL-10 and TGF-β1 are expressed in cervical lesions; therefore, the development of SIL and cervical cancer is preferentially associated with the expression of immunosuppressive cytokines (IL-10 and TGF-β1) and Th2-type cytokines (IL-4/IL-6)." (PMID 24808638, 2014). "Also, we observed the elevated levels of TGF-β, IL-6, IL-17 and IL-21 in cervical cancers (unpublished observations)." (PMID 24523865, 2014). "In view of the fact that E6 is known to activate IL-6/STAT3 signaling in cervical cancer cells, our results demonstrate existence of HPV16 E6-induced proinflammatory signaling that operate through STAT3 and miR-21 by blocking its negative regulators Let-7a and PTEN." (PMID 25539644, 2014). "Inflammatory cytokine IL-6, a potent inducer of STAT3 activity through binding to gp130 associated receptors and Jak/Tyk kinases, has received particular attention in the pathogenesis of cervical cancer." (PMID 20977777, 2010). "Stat3 activation in cervical cancer is also largely unclear but one of the mechanisms may be involved in interleukin-6." (PMID 17311011, 2007).
cervical carcinoma (continued). "In this context, our findings of lower risk of cervical cancer after PE suggest that immune regulation in these women, such as elevated TNF-α, IL-6, and IL-7 responses along with enhanced cytotoxic T-cell activation, might reduce the risk of persistent HPV infection." (PMID 40610749, 2025). "Thrombocythemia, high PLR (platelet to lymphocyte ratio) and IL-6 overexpression correlated with cervical cancer progression and metastasis, they may play an important role as molecular markers of survival and may be considered as potential predictors of cervical cancer prognosis." (PMID 37914994, 2023). "A positive correlation was observed between IL-6, IL-8, IL-12p70, IL-17, and IFN-γ levels (P < 0.05), suggesting that these cytokines may associated with 5-year relapse rates and/or the metastasis of cervical cancer." (PMID 36053326, 2023). "Therefore, we next analyzed whether Orai1-regulated SOCE plays a key role in the expression and secretion of IL-6 in cervical cancer." (PMID 36310590, 2022). "However, the contribution of IL-6 to STAT3 activity in cervical cancer is not well understood." (PMID 34445405, 2021). "Nevertheless, our observations suggest that when poly(I:C) is selected as a therapeutic vaccine for cervical cancer, special attention should be paid to its effect on the local microenvironment of the tumour, and relevant measures should be taken to inhibit its promotion of IL‐6 secretion." (PMID 31943744, 2020). "Finally, we demonstrate a correlation between NFκB activation, IL-6 expression and cervical disease progression, suggesting that targeting the IL-6 pathway to prevent STAT3 activation may have therapeutic benefits in cervical cancer." (PMID 31226168, 2019). "Notably, both CCR7 and MMP-9 up-regulation are mediated by IL-6 from the cervical cancer cells." (PMID 28895886, 2017). "For instance, IL-6 blockade via monoclonal antibodies or JAK/STAT3 inhibitors has demonstrated early promise in solid tumors, including cervical cancer, by reducing proliferation, reversing EMT, and sensitizing tumor cells to chemotherapy and radiotherapy." (PMID 41497141, 2026). "Cytokines such as IL-6 and TNF-α are pivotal mediators of the inflammatory microenvironment in cervical cancer, yet their roles are complex and context-dependent." (PMID 41497141, 2026). "In cervical cancer, persistent HPV infection shifts the balance towards chronic low-grade inflammation where IL-6 and TNF-α predominantly support tumorigenesis." (PMID 41497141, 2026). "In vitro, ADU-S100 (a STING agonist)-treated cervical cancer cells exhibited reduced cell viability in a dose-dependent manner, accompanied by the upregulation of STING/IFN-β/IL-6 expression." (PMID 41142804, 2025). "The knockdown of STING increased the viability and migration of cervical cancer cells, accompanied by the reduction of IFN-β and IL-6 mRNA expression following dsDNA stimulation." (PMID 41142804, 2025). "Within the cervical cancer microenvironment, monocyte differentiation into dendritic cells is impaired, while prostaglandin E2 (PGE2) and interleukin-6 (IL-6) secreted by cancer cells induce differentiation into M2 macrophages." (PMID 40264780, 2025). "Previous studies have shown that activation of the IL-6 signaling axis induces the autocrine and paracrine phosphorylation of STAT3 in HPV-positive cervical cancer cells, where this pathway is crucial for cancer cell proliferation and survival." (PMID 40143240, 2025). "The extract exhibited dose-dependent suppression of interleukin-6 (IL-6), interleukin-8 (IL-8), and monocyte chemoattractant protein-1 (MCP-1) expression in both human cervical cancer (HeLa) and murine fibroblast (L929) cells." (PMID 39844243, 2025). "Addition of human recombinant IL-6 and IL-8 to CAF-CM after anlotinib treatment restored their promotional effects on proliferation and invasion of cervical cancer cells." (PMID 39193386, 2024).
cervical carcinoma (continued). "In this study, our findings showed that preoperation plasma levels of sHLA-G and the cytokines IL-6, IL-10, and IFN-γ in cervical cancer patients had a good discriminatory effect between cervical cancer patients and healthy women." (PMID 36053326, 2023). "The PPI network showed that IL6, VEGFA, and FGF2 are the key targets of seabuckthorn polysaccharides in the prevention and treatment of cervical cancer." (PMID 36845055, 2023). "A reduced expression of E-cadherin was reported as a result of TGF-β treatment of cervical cancer cells, TNF-α treatment, IL-6 treatment, and treatment with Chemokine (C–C motif) ligand 20 (CCL20)." (PMID 36766756, 2023). "Vimentin was found to be upregulated by treatment of cervical cancer cells with TGF-β; IL-6; and with chemokine CCL20." (PMID 36766756, 2023). "We can still identify some genes related to cervical cancer progression from the samples of the two patients after treatment, including ATF3, GPX3, IL10, IL6, RAD51AP1, MGMT, WWOX." (PMID 37914994, 2023). "The level of cytokines such as IL-6, IL-10, IL-8, TNF-α, and VEGF can be co-related with disease progression in ovarian, breast, and cervical carcinoma." (PMID 37746258, 2023). "The autocrine activation of IL-6 is responsible for STAT3 phosphorylation in HPV-related malignancies, particularly in cervical cancer." (PMID 36405719, 2022). "IL6 can also lead to STAT3 activation, and this pathway contributes to cell proliferation and survival of cervical cancer cells." (PMID 35468924, 2022). "Here we show that the expression of IL6 and IL18 is modulated by TLR4 and SARM1 in cervical cancer cells." (PMID 35468924, 2022). "Blocking IL-6 and GP130 signaling in HPV-positive cervical cancer cells abolished STAT3 phosphorylation, and blocking the GP130 signal was found to be a major determinant of STAT3 phosphorylation." (PMID 34445405, 2021). "Recent studies have shown that in cervical cancer, Poly(I:C), an adjuvant for cancer vaccine, may act through the NF-κB signaling pathway to promote the expression of M1-type cytokines (such as IL-1β and IL-6) and inhibit the expression of M2-type cytokines (such as IL-10 and CCL22)." (PMID 34717710, 2021). "In previous studies, T. vaginalis infection induced the production of inflammatory cytokines such as IL-1β, IL-6, CCL2 and CXCL8 in prostate epithelial cells as well as cervical cancer cells." (PMID 32196489, 2020). "The SIRPα knockdown in DCs results in increased cytokine (TNF-α/IL-12/IL-6) secretion, IFN-γ secretion by T lymphocytes, and in vitro/in vivo tumoricidal activity against cervical cancer." (PMID 32411788, 2020). "HeLa and SiHa cells were treated with RES, IL‐6, and their combination, then, their STAT3 Tyr705 was detected to further examine the role of RES in the regulation of STAT3 phosphorylation in cervical cancer cells." (PMID 33040485, 2020). "Human papillomavirus (HPV) positive cervical cancer cell lines have also been shown to have elevated pTyr705 STAT3 levels, which is driven by exacerbated IL-6 secretion." (PMID 32915198, 2020). "The elevated IL‐6 level in cervical cancer supernatant regulated the secretion profile of THP‐1–derived macrophages and promoted the recruitment of macrophages by cervical cancer supernatant." (PMID 31943744, 2020). "HPV16 and HPV18 E6 oncoproteins have been demonstrated to be required for the expression and secretion of IL-6 in NSCLC cells; however, the role of E6 in driving IL-6 expression in cervical cancer is unclear." (PMID 31226168, 2019). "To examine the clinical relevance of the MUC1-EGFR-IL-6 axis in cancer patients, we collected 20 paired pre- and post-NACT tumor specimens from cervical cancer patients and performed immunohistochemistry to detect the expression of MUC1, EGFR, and IL-6." (PMID 31772161, 2019). "To investigate if such a positive feedback loop exists in cervical cancer cells we used siRNA to deplete STAT3 from HeLa and CaSKi cells and then measured the impact on IL-6 expression." (PMID 31226168, 2019).
cervical carcinoma (continued). "Pretreatment with TMS-TMF-4f reduced the green fluorescence intensity (IL-6-induced STAT3 phosphorylation) and p-STAT protein levels in both HeLa and CaSki cervical cancer cells." (PMID 31816985, 2019). "The data presented here demonstrate that NFκB is essential for the induction of IL-6 and the autocrine/paracrine induction of STAT3 phosphorylation in HPV+ cervical cancer cells." (PMID 31226168, 2019). "IL-6 and gp130 blocking antibodies were utilised to interrogate their requirement for STAT3 phosphorylation in cervical cancer cells." (PMID 31226168, 2019). "Enhanced the antioxidant enzyme activities, and reduced levels of IL-1b, IL-6, and TNF-α in rats with cervical cancer." (PMID 30410443, 2018). "During our research, miR-218 overexpression inhibited the expression and function of these inflammatory factors TGF-β, VEGF, IL-6, PGE2, and COX-2 in cervical cancer cells." (PMID 30314496, 2018). "In cultured cervical cancer cells, however, efficient STAT3 activation can only be elicited by IL-6 in the presence of soluble gp80 (sgp80)." (PMID 28895886, 2017). "Meanwhile, IL-6 is one of the key activators of STAT3, so we treated it to cervical cancer cell lines to reveal the relationship among IL-6R/LYN/STAT3." (PMID 27690342, 2016). "This indicated an option to deprive the activated IL-6/STAT3 network against inflammation including fibroblast senescence in tumor microenvironment which may be considered as a complement to increase the efficacy of the targeted therapy against HPV 16/18 in cervical cancer." (PMID 26308848, 2015). "Another EMT-related cytokine, interleukin-6 induced EMT through signal transducer and activator of transcription 3 in human cervical carcinoma." (PMID 25590298, 2015). "A study comprising 91 cervical cancer cases discovered a correlation between low hemoglobin and elevated levels of reactive oxygen species, CRP, IL-1, TNF-α, ß, and IL-6, multivariate analysis revealed that IL-6 was a separate factor influencing hemoglobin levels." (PMID 41142623, 2025). "Conversely, senescent fibroblasts secrete elevated levels of inflammatory cytokines (including IL-6), which further activate STAT3 in an autocrine manner and regulate the tumor microenvironment, thus resulting in resistance and recurrence of cervical cancer after radiotherapy." (PMID 38651153, 2024). "IL-6, TNF-α, and granulocyte-colony-stimulating factor (G-CSF) have been identified as significant contributors to neutrophilia in various malignancies, including anal cancer, cervical cancer, and CRC." (PMID 38041687, 2024). "Furthermore, pro-inflammatory cytokines, such as COX-2, iNOS, IL-6, IL-8, MIP-3α, TGF-β1, and VEGF, are upregulated in HPV-related cervical cancer cells in vivo following the activation of the TLR4/MyD88/NF-KB pathway." (PMID 39451550, 2024). "Moreover, GLPs reduced the expression of pro-inflammatory cytokines, such as IL-1β (interleukin-1β), IL-6 (interleukin-6), and TNF-α (tumor necrosis factor-alpha), in rats with cervical cancer." (PMID 38104078, 2023). "Since cervical carcinoma patients often have persistent HPV infection, Nr‐CWS may promote the function of IL‐6 and IL‐1β against foreign pathogens." (PMID 34994088, 2022). "A number of studies have confirmed that STAT3 phosphorylation is also increased in cervical cancer; this is achieved through increased NFκB signalling and autocrine/paracrine activation of STAT3 by the pro-inflammatory cytokine interleukin-6 (IL-6)." (PMID 33427604, 2021). "In order to further verify our screening results, we selected C6- quercetin, an important active compound in the treatment of cervical cancer by Hedyotis diffusa, for molecular docking with the core targets IL1B and IL6 which have prognostic value for cervical cancer respectively." (PMID 34975504, 2021).
cervical carcinoma (continued). "Similarly, in human cervical carcinoma cells (Hela), HIF-1α, IL-1β, IL-6, and IFN-β mRNAs were promoted by VSV infection, HSV-1 infection and poly(I: C) treatment and HIF-1α protein was induced by VSV infection, HSV-1 infection or poly(I: C) treatment." (PMID 34408131, 2021). "In addition, we found that ICA inhibited cervical cancer SiHa cells proliferation, migration, invasion, and the expression levels of TGF-β1, TNF-α, IL-6, IL-17A, and IL-10, as well as promoted cell apoptosis." (PMID 33849528, 2021). "IL-6 is capable of promoting the growth of cervical tumor cells and is involved in tumor angiogenesis through the regulation of VEGF during the early stages of cervical cancer." (PMID 33750983, 2021). "Furthermore, we found that TLR4 promoted the expression of proinflammatory cytokines such as COX-2, iNOS, IL-6, IL-8, MIP-3α, TGF-β1 and VEGF in HPV-related cervical cancer cells in vivo." (PMID 32095158, 2020). "Besides cervical cancer cells, the effect of HPV16/18 E6 and E7 on upregulating IL-6 expression has been reported in E6- and E7-transfected A549 cells, which are a non-small cell lung cancer cell line." (PMID 31470515, 2019). "As KP exhibits the ability to impede the tumorigenic influence of EGFR and IL-6 signaling in HeLa cells, we believe that KP could be a good candidate to be developed as an agent for treating HPV18-positive cervical cancer." (PMID 31470515, 2019). "As STAT3 can be activated by several soluble factors in cervical cancer cells, such as OSM, EGF and IL-10, it is possible that the IL-6 low cancers might be dependent on these additional cytokines to maintain active STAT3." (PMID 31226168, 2019). "The explanation for this phenomenon may be because of the fact that HeLa cervical cancer cells contain HPV-18 sequence, which stimulates constitutive expression of IL-6." (PMID 31470515, 2019). "Specifically, it is well known that NF-kB regulates Mcl-1 and IL-6 expression, and these two proteins are also highly expressed in invasive cervical cancer, but not in normal cervical tissues." (PMID 31470515, 2019). "We reveal that activation of an IL-6 signalling axis drives the autocrine and paracrine phosphorylation of STAT3 within HPV positive cervical cancers cells and that activation of this pathway is essential for cervical cancer cell proliferation and survival." (PMID 31226168, 2019). "Interleukin-6 (IL-6) is a 26 K.D cytokine synthesized by vascular endothelial cells and mononuclear phagocytes fibroblasts encountered in bladder and cervical cancer." (PMID 30648081, 2018). "In order to determine whether IL-6 could regulate LYN expression in cervical cancer cell lines, we analyzed LYN expression in SiHa and C33a cells after IL-6 treatment." (PMID 27690342, 2016). "Measuring IL6, IL5 and IL17 expression may improve the accuracy of predicting prognosis in cervical cancer." (PMID 25889974, 2015). "The basic research showed that P2 could suppress the production of nitric oxide in LPS-induced RAW264.7 macrophage cells as well as the secretion of inflammatory cytokines IL-6 and TNF-α in human cervical cancer HeLa cells." (PMID 24683359, 2014). "Non-malignant HPV-transformed keratinocytes and cervical carcinoma cells produce large quantities of IL-6." (PMID 20977777, 2010). "Our findings indicate that a composite biomarker panel comprising SCC-Ag, CA125, IL-6, and NLR achieves superior predictive performance for both treatment response and survival compared to single-marker models in patients with locally advanced cervical cancer undergoing chemoradiotherapy." (PMID 41244922, 2025). "In addition, our findings showed that the levels of cytokines IL-6, IL-8, IL-12p70, IL-17, and IFN-γ may be related to 5-year relapse rates and/or the metastasis of cervical cancer." (PMID 36053326, 2023).